CXCL1 (C-X-C motif chemokine ligand 1)
Diseases named in the same sentence as CXCL1 in open-access papers (continued):
Sharing a sentence is not in itself a finding about the gene and the disease.
psoriasis (continued). "To understand the molecular mechanism of N4BP1 in the regulation of neutrophil infiltration, we examined the mRNA level of several key genes involved in inflammation including TNFa, IL-23, IL-17, CXCL1, CCL20, S100A8, and S100A9 in psoriasis skin from N4BP1 KO and WT mice." (PMID 33990547, 2021). "Unexpectedly, pro-inflammatory genes, including CXCL1, CCL2, and IL-1β, which may lead to severe inflammation in psoriasis patients, were downregulated by miR-193b-3p mimics in the presence or absence of M5 treatment." (PMID 34667159, 2021). "Furthermore, Cl-amidine-treated Il36rn−/− mice with psoriasis-like lesions showed decreased TNF-α, CXCL1, IL-1β, IL-36γ, and IL-17A expression compared to those in untreated, IMQ-induced Il36rn−/− mice." (PMID 33214582, 2020). "In addition, TNF-α, CXCL1, IL-1β, IL-17A, and IL-36γ mRNA expression levels in IMQ-induced psoriasis-like lesions were significantly reduced by Cl-amidine administration compared to those in vehicle-treated Il36rn−/− mice." (PMID 33214582, 2020). "In addition, real-time RT-PCR analysis showed that IL-1β, IL-17A, IL-36γ, CXCL1, and CXCL2 expression was increased in IMQ-induced psoriasis-like lesions in Il36rn−/− mice." (PMID 33214582, 2020). "In aggregate, these results suggest that neutrophils recruitment (a prominent feature of human psoriasis and many murine models of psoriasis) is, in part, regulated by TRPA1 through modulation of expression of neutrophil chemoattractants such as CXCL1 and CXCL2." (PMID 31111624, 2019). "Notably, the “Role of IL-17A in Psoriasis” (T2, −log(FDR) = 1.67) pathway was enriched, in which downregulated CXCL3, IL-8, S100A8, S100A9, IL17RA and CXCL1 expression was observed." (PMID 29871627, 2018). "The expression of Th1 and Th17 recruiting chemokines CXCL1, CXCL8 and CCL20 is upregulated in psoriasis skin but the precise contribution of DCs to chemokine secretion in psoriasis is unknown." (PMID 25301671, 2015). "Similarly, the pathogenesis of psoriasis involves key Th1 and Th17 inducing cytokines like TNFα, IL-1β, IL-2, IL-6, IL-10, IL-12p70, IL-23, CCL2, 3, 4, 5, 20, CXCL1, 8, 9 and 10, many of which are induced by cocktail treated DCs." (PMID 20663192, 2010). "Immunohistochemical, western blot, and multiplex analysis showed that the TLR activation induced the expression of psoriasis associated markers like S100A7, p-STAT3, CXCL-1, IL-8, IL-1α, S100A9, and IL-23 in the wild type but not in the TLR KO epidermis models." (PMID 40995100, 2025). "However, notable differences were noticed in the amounts of IL-1α (3.14 vs. 0.98 ng/mL) and CXCL-1/2 (not detected vs. 0.06 ng/mL) when compared between healthy volunteers and lesional skin of psoriasis patients (p < 0.001 and p < 0.01, respectively)." (PMID 36936209, 2023). "Many immune-derived cytokines and chemokines, including IL-17, IL-23, IL-6, C-X-C motif ligand-1 (CXCL-1), TNF-α, and p65, can drive inflammatory cell infiltration and an inflammation loop, thus regulating keratinocyte proliferation and leading to the development and maintenance of psoriasis." (PMID 35216231, 2022). "A comparative study revealed differential expression of chemokines in AD (CCL17/18/20) and psoriasis (CXCL1, IL-8, and CCL20), indicating that disease-specific microenvironments might be involved in Th differentiation While psoriasis is Th17/Th22-skewing, AD tends to be Th2/Th22 polarized." (PMID 35911703, 2022). "Furthermore, IL-1β stimulation of NHEKs was found to induce upregulation of the mRNA and protein levels of pro-inflammatory cytokines, chemokines and antibiotic peptides including IL-36γ, CXCL1, CXCL2, CCL20, S100A7, S100A8 and S100A9, which are closely related to the pathogenesis of psoriasis." (PMID 32194991, 2020).
psoriasis (continued). "UVB irradiation inhibits IL-17A/TNF-α-induced IL-6, IL-8, and CXCL-1 production in HDFs by decreasing the expression of IL-17RA and IL-17RC on fibroblasts through TGF-β1/Smad3 signaling pathway, which reveals a new mechanism of the therapeutic action of UVB on psoriasis." (PMID 28217129, 2017). "Our results confirm that UVB irradiation inhibits IL-17A/TNF-α-induced IL-6, IL-8, and CXCL-1 production in HDFs by decreasing the expression of IL-17RA and IL-17RC on fibroblasts through TGF-β1/Smad3 pathway, which reveals a new mechanism of the therapeutic action of UVB on psoriasis." (PMID 28217129, 2017). "Additionally, expression of CCL2 mRNA was significantly induced, and there were mild (but not statistically significant) increases in CXCL1, CXCL10, CCL5, and IL-8 in psoriasis-associated mutant CARD14 transfected HDBECs compared to wild-type HDBECs." (PMID 25369198, 2014). "The list of the DEG in common in the 4 studies contains many genes known to be upregulated in psoriasis, such as IFNγ-regulated genes STAT-1, STAT-3 and MX1; antimicrobial peptides (beta defensin 4, lipocalin 2, S100A7); and pro-inflammatory proteins such as IL-8, CXCL1, IL-1F9, TNFSF10/TRAIL." (PMID 20422035, 2010). "However, a significant number of genes which may be induced by IL-23 or IL-22 such as GRO-1 (CXCL1), S100A7, S100A8, STAT3, IL-6, SCYA20 (CCL20), SCYA22 (macrophage-derived chemokine/CCL22), and β-defensin 2 have been identified in psoriasis microarray studies." (PMID 19884985, 2009).
colorectal cancer (81 papers, 2008 to 2026). A primary or metastatic malignant neoplasm that affects the colon or rectum. "SMAD4 deficiency promotes the progression of colorectal cancer by attracting tumor-associated neutrophils through the CXCL1/8-CXCR2 axis." (PMID 39100676, 2024). "C-X-C motif ligand 1 (CXCL1) is a growth factor exerting chemotaxis for neutrophils, for which aberrant expression is associated with colorectal cancer progression, including metastasis." (PMID 39167197, 2024). "Other studies have shown that CXCL1 is associated with a worse prognosis only in patients with stage III colorectal cancer or only in stage IV." (PMID 37408240, 2023). "CXCL1 also causes the migration and invasion of colorectal cancer cells, which is associated with an increase in MMP7 expression, and CXCL1 causing EMT of cancer cells." (PMID 37408240, 2023). "High levels of CXCL1 in the blood are correlated with levels of circulating tumor cells, which indicates that CXCL1 is associated with a high likelihood of colorectal cancer metastasis." (PMID 37408240, 2023). "As CXCL1 is a chemotactic factor for neutrophils, an increase in CXCL1 expression in colorectal cancer tumors results in the recruitment of tumor-associated neutrophils (TAN), cells with pro-cancer properties." (PMID 35054978, 2022). "There is increasing evidence that the chemokine CXCL1 is associated with metastatic spread in colorectal cancer, with high CXCL1 tumor expression associated with poorer prognosis and survival." (PMID 31132111, 2019). "In colorectal cancer, VEGF secretion by colorectal carcinoma cells stimulates tumor-associated macrophages (TAMs) to produce chemokine (C-X-C motif) ligand 1 (CXCL1), which recruits C-X-C motif chemokine receptor 2 (CXCR2)+ MDSCs to the liver tissue." (PMID 30792719, 2019). "Similarly, CXCL1 overexpression in colorectal cancer has been linked to enhanced tumor angiogenesis and recruitment of M2-like TAMs, further supporting an immunosuppressive tumor microenvironment." (PMID 40330466, 2025). "Moreover, the secretion of VEGFA by colorectal cancer cells induces tumor-associated macrophages to produce CXCL1 and attract MDSCs, leading to the formation of a premetastatic niche that facilitates the development of liver metastases." (PMID 38555418, 2024). "A higher level of CXCL1 in the blood of a colorectal cancer patient is associated with a higher TNM stage and may be an indicator of lung metastasis." (PMID 37408240, 2023). "CXCL1 may also facilitate the formation of metastasis by inducing an increase in parathyroid hormone-like hormone (PTHLH) expression in colorectal cancer cells —a factor that causes bone remodeling during the formation of bone metastasis." (PMID 37408240, 2023). "In addition, CXCL1 in colorectal cancer tumors causes angiogenesis and stromal fibroblast senescence which alters the secretory phenotype of these cells and thus enhances cancer tumor growth." (PMID 37408240, 2023). "In addition, we evaluated its diagnostic value, and staged colorectal cancer phenotypes with high and low CXCL1 expression according to the median expression level." (PMID 36434686, 2022). "In our previous study, we found high expression of CXCL1 in colorectal cancer and its close correlation with the clinicopathological features; in addition, CXCL1 overexpression was closely associated with tumor diameter, stage, degree of infiltration, and lymph node metastasis." (PMID 36434686, 2022). "In addition, an inverse association between CXCL1 and recurrence-free survival was observed in colorectal cancer patients." (PMID 24376747, 2013). "Thus CXCL1 has been associated with tumor size, tumor stage, invasion, metastasis and survival in colorectal cancer patients." (PMID 24376747, 2013). "Increased CXCL1 expression in colorectal cancer cells may also be associated with adiponectin." (PMID 37408240, 2023). "In colorectal cancer, a high CXCL1/5 expression is maintained via the CXCR/MMPI/epidermal growth factor (EGF) pathway." (PMID 40076892, 2025).
colorectal cancer (continued). "CXCL1 supports the proliferation of colorectal cancer cells by activating the NF-κB/P300 signaling pathway." (PMID 39595551, 2024). "Colorectal cancer cell-derived CXCL1 promotes the secretion of epithelial growth factor (EGF) in an autocrine manner by binding to CXCR2 in colorectal cancer cells." (PMID 38713320, 2024). "More specifically, NF-κB subunit p65/Rela is the direct target of YTHDF1 that upregulates chemokine CXCL1 expression in colorectal cancer cells, promoting the infiltration of PMN-MDSCs into the TME." (PMID 39133578, 2024). "Genetic or pharmacologic inhibition of m6A writer METTL3 reduces the infiltration of MDSCs in lung cancer and PMN-MDSCs in colorectal cancer by reducing the expression of chemokines CXCL1, CXCL5, and CCL20." (PMID 39133578, 2024). "It has been reported that colorectal cancer cell-derived CXCL1 promotes the secretion of epithelial growth factor (EGF) in an autocrine manner by binding to C-X-C motif chemokine receptor 2 (CXCR2) in colorectal cancer cells." (PMID 38713320, 2024). "Chemokine (C-X-C motif) ligands, CXCL1-17, comprise a vast family, with some members serving as prognostic biomarkers in colorectal carcinoma." (PMID 38844562, 2024). "Knockdown of SMAD4 in human colorectal carcinoma cells leads to increased expression of CXCL1 and CXCL8, indicating cross-talk between TGF and CXCL signaling pathways and neutrophil recruitment." (PMID 38844562, 2024). "A recent study indicates that the re–lease of CXCL1 directly contributes to the development of metastases in colorectal cancer." (PMID 36614235, 2023). "Further, mutation in Ras proteins can cause an increase in the activity of these proteins and lead to an increase in CXCL1 expression in colorectal cancer cells." (PMID 37408240, 2023). "The results of studies on the relationship between CXCL1 levels in the tumor and prognosis for the colorectal cancer patient are varied." (PMID 37408240, 2023). "In regards to CXCL1 in other cancers, the level of CXCL1 expression in colorectal cancer tissues was significantly higher than in adjacent normal tissues and positively correlated with the size of the tumor and its stage of progression." (PMID 36614235, 2023). "Due to links in tumor mechanisms with other proteins, CXCL1 is considered a hub gene in colorectal cancer." (PMID 37408240, 2023). "CXCL1 expression in colorectal cancer cells is also increased by prostaglandin E2 (PGE2) in a process that depends on the EGFR-MAPK pathway." (PMID 37408240, 2023). "In the present study, we applied bioinformatics analysis and identified increased expression of CXCL1 in colorectal cancer." (PMID 36434686, 2022). "We first verified the differential expression of CXCL1 in colorectal cancer, and found significantly higher expression of CXCL1 in colorectal cancer compared to that in normal tissues." (PMID 36434686, 2022). "Expression data of CXCL1 in colorectal cancer were obtained from the GEO database and verified using the GEPIA database and the TIMER 2.0 database." (PMID 36434686, 2022). "Bioinformatics analysis showed significant overexpression of CXCL1 in the colorectal cancer tissues compared to normal human tissues, and identified CXCL1 as a potential therapeutic target for colorectal cancer." (PMID 36434686, 2022). "CXCL1 expression was significantly higher in colorectal cancer tissues than in the paratumoral normal tissues." (PMID 36434686, 2022). "CXCL1 has also been linked to a poor prognosis in patients with gastric cancer, HNSCC, glioblastoma, and colorectal cancer." (PMID 35626430, 2022). "The current study was designed to study the molecular mechanism by which CXCL1 promotes the progression of colorectal cancer." (PMID 36434686, 2022). "Receiver operating characteristic (ROC) curve showed that CXCL1 had a high accuracy for the diagnosis of colorectal cancer [area under the curve (AUC) (95% CI): 0.928 (0.893–0.963)]." (PMID 36434686, 2022).
colorectal cancer (continued). "To further investigate the effect of CXCL1 on colorectal cancer, we compared the expression of CXCL1 in colorectal cancer tissues and paratumoral normal tissues of patients with colorectal cancer using the TCGA database." (PMID 36434686, 2022). "The function and mechanism of action of CXCL1 have seldom been researched in the context of colorectal cancer." (PMID 36434686, 2022). "Knockout and overexpression of CXCL1 in colorectal cancer cells by CRISPR/Cas and "Sleeping Beauty" transposon-mediated gene editing techniques." (PMID 36434686, 2022). "Subsequently, we explored the role of CXCL1 in colorectal cancer from the perspective of cell biological behavior." (PMID 36434686, 2022). "For example, in colorectal cancer tissue, CXCL1, CXCL2, CXCL3, CXCL5, CXCL8, and CXCL11 were highly expressed, while CXCL12, CXCL13, and CXCL14 were little expressed." (PMID 36612163, 2022). "CXCL1 is also critical in facilitating PMN formation in colorectal cancer by recruiting CXCR2+ MDSCs." (PMID 33463063, 2021). "Mechanistically, colorectal cancer cells stimulate TAMs to produce CXCL1 by secreting VEGFA, and CXCL1 recruits CXCR2+ MDSCs from the blood into the pre-metastatic liver." (PMID 34527668, 2021). "In the serum of patients with colorectal cancer, CXCL1 is a predictive marker for lung and liver metastases." (PMID 33572437, 2021). "We report the molecular docking analysis of antimicrobial peptides MREEKKERKRD and MVQGAKRGGRLHRV with the target protein CXCL1 for colorectal cancer for further consideration intherapy and development." (PMID 34092958, 2021). "In previous studies, multiple studies reported the prognostic value of CXCL1 in colorectal cancer 36-38, and there were reports verifying the molecular mechanism of CXCL1 in colorectal cancer through in vivo and in vitro experiments 39-43." (PMID 34405013, 2021). "The transcription levels of CXCL1 in colorectal carcinoma were higher than those in colorectal tissues in all 10 datasets." (PMID 34233297, 2021). "Overexpression of CXCL1 has been found in several malignant tumors, such as pancreatic cancer, colorectal carcinoma, bladder cancer, liver cancer, and oral squamous carcinoma." (PMID 34269159, 2021). "Colorectal carcinoma cells secrete VEGFA, which stimulates tumor-associated macrophages to produce CXCL1 in the primary tumor." (PMID 34907282, 2021). "This study made a systemic description for the CXCL1-dependent regulatory mechanism in colorectal cancer (CRC)." (PMID 34079750, 2020). "The role of CXCL1 in glioma is poorly described, however in breast and colorectal cancer it is depicted as promoter of metastasis and involved in the formation of the premetastatic niche." (PMID 33066172, 2020). "Significantly elevated expression of IL1-β, IL-6, IL-8, IL-10, IL-17, TNF-α, TGF-β, IFN-γ, and C-X-C motif chemokine ligand 1 (CXCL1) has been seen in colorectal cancer and other solid cancers like lung cancer." (PMID 32425932, 2020). "Silencing of CXCL1 can inhibit tumor growth in hepatocellular carcinoma, while knockdown of CXCL1 expression can inhibit tumor growth in colorectal cancer liver metastasis." (PMID 32079335, 2020). "The close interplay among these mediators is demonstrated by the up-regulation of CXCL5 and CXCL8 expression in human non-small cell lung cancer cells and of CXCL1 in colorectal cancer cells induced by PTGS2." (PMID 31920649, 2019). "CXCL1 was essential for pre-metastatic niche formation and metastasis of colorectal cancer by modulating the microenvironmental pathways." (PMID 31438997, 2019). "CXCL1 and CXCL8 that are associated with colorectal cancer risk and overall survival, appeared to be included in epithelial cell signaling in Helicobacter pylori (H. pylori) infection, chemokine signaling pathway and cytokine-cytokine receptor interaction." (PMID 30642095, 2019). "CXCL1 hypersecretion from colorectal cancers' epithelia and myofibroblasts was also related with poor prognosis." (PMID 28575019, 2017).